HMGB1 (high mobility group box 1)
Diseases named in the same sentence as HMGB1 in open-access papers (continued):
Sharing a sentence is not in itself a finding about the gene and the disease.
tumor (continued). "Consequently, HMGB1 acts through TLR4 expressed in DCs increasing their capability to present antigens of dying tumour cells." (PMID 23551576, 2013). "HMGB1 exerts its angio-genetic effects via the RAGE pathway in tumor cells; it has been demonstrated to increase the expression of angiogenic growth factors, including VEGF, and to attract macrophages, which also produce a number of potent angiogenetic cytokines and growth factors." (PMID 23426143, 2013). "Furthermore, their study also showed that HMGB1 is released in the serum during tumor progression correlating with severity of disease pathology." (PMID 23766911, 2013). "Thus, we have attempted to determine if HMGB1 promotes tumor metastasis by upregulating the expression of VEGF-C or if each protein exerts its function independently." (PMID 23866030, 2013). "Our study suggests that effects on tumor cells through stimulation of TLRs by endogenous ligands such as soluble syndecan-1, matrix metalloproteinase products, heat-shock proteins, HMGB-1, which are released due to cell necrosis, should also be considered in MM." (PMID 23593278, 2013). "Moreover, HMGB1 passively released from tumor cells interact with TLR4 on DCs, and result in the stimulation, antigen-processing and -presentation in DCs." (PMID 23717436, 2013). "The overexpression of HMGB/HMGB2 was correlated with both the clinical stage and pathological grade of the tumor, and HMGB1 and HMGB2 may be involved in BCa development and progression." (PMID 23426143, 2013). "It has also been postulated to inhibit tumor angiogenesis by disrupting HMGB1-RAGE signaling." (PMID 23766911, 2013). "However, the cellular and molecular immune mechanisms of Hmgb1 in the development of tumor remain elusive." (PMID 24453427, 2013). "Therefore, in the scenario where TIM-3 sequester HMGB1 to nucleic acids, the innate immune responses toward the tumor are blocked resulting in increased tumor expansion." (PMID 23316202, 2012). "Different models indicated the HMGB1 protein had beneficial influence on tumor development." (PMID 22747650, 2012). "Our results showed that the expression of HMGB1 was significantly higher in tumor tissue than that in para-tumor and normal tissue, which indicated that HMGB1 might play an important part in the carcinogenesis of HCC." (PMID 22747650, 2012). "High mobility group box 1 (HMGB1) is a nuclear chromatin-binding protein that can also be secreted in the extracellular environment, functioning as a signaling molecule in e.g., inflammation, cell migration and tumor metastasis." (PMID 24710477, 2012). "Multivariate analysis showed that high expression of HMGB1 was an independent prognostic factor for both overall (p = 0.009, HR = 1.834, 95%CI: 1.167-2.881) and disease-free survival (p = 0.018, HR = 1.622, 95%CI: 1.088-2.419), along with tumor size." (PMID 22747650, 2012). "Studies from Zitvogel's group have characterized several prominent features of immunogenic cell death after cytotoxic chemotherapy, including translocation of calreticulin (CRT), secretion of high-mobility-group box 1 (HMGB1), and release of adenosine triphosphate (ATP) by dying tumor cells." (PMID 22400040, 2012). "HMGB1 secreted from tumor cells can be involved in tumor progression, particularly metastasis." (PMID 22496788, 2012). "HMGB1 was expressed in the nuclei of both normal and tumor cells." (PMID 22496788, 2012). "HMGB1 released from tumor cells binds to TLR4 on DCs, thus contributing to DC activation." (PMID 22891162, 2012). "The authors hypothesize that HMGB1 is released by necrotic tumor cells and enhances cell resistance by activating RAGE, inducing autophagy, and inhibiting apoptosis." (PMID 22291707, 2012). "In solid tumors, cells that are not adapted to metabolic constraints such as hypoxia and GD die by necrosis as ‘a reparative cell death’ that could promote tumor progression by releasing the tumor-promoting cytokine HMGB1." (PMID 21448462, 2011).
tumor (continued). "In murine models, RF ablation induced strong upregulation of mRNA and/or protein levels of HSP-70, HSP-90, and glycoprotein 96 (gp96) as well as translocation of nuclear high-mobility group protein B1 (HMGB1) into the cytoplasm of tumor cells and into the intercellular space." (PMID 22242035, 2011). "Thus, HMGB1 acts as a pro-inflammatory and tumor-promoting cytokine when released into the extracellular space during necrosis." (PMID 21917150, 2011). "HMGB1 could therefore activate DCs and prevent the accelerated degradation of the phagocytosed tumor antigens within DCs promoting efficient tumor antigen processing and cross-presentation." (PMID 22110526, 2011). "HMGB1 is connected in several ways to tumor progression and metastasis." (PMID 22110526, 2011). "But the tumor stage and HMGB1 overexpression showed the correlation with cancer-free survival." (PMID 20579387, 2010). "While, primary tumor infiltrating depth perhaps correlated with HMGB1 overexpression." (PMID 20579387, 2010). "The interaction of HMGB1 protein released from dying tumor cells with TLR4 on DCs was required for the cross-presentation of tumor antigens and the promotion of tumor specific cytotoxic T-cell responses, which are selectively involved in the cross-priming of anti-tumor T lymphocytes in vivo." (PMID 20579387, 2010). "In addition, extracellular HMGB1 triggers the inflammatory cascade through multiple pathways, facilitating progression of the tumor." (PMID 20846416, 2010). "HMGB1 could be measured in serum and used as a serologic tumor biomarker because it can be released into extracellular environment like other cytokines." (PMID 19476625, 2009). "A recent study found that HMGB1 could be detected in the serum of cancer patients because it can be passively released from dying tumor cells, or actively released from immune cells into the extra-cellular space or serum." (PMID 19476625, 2009). "The constant release of HMGB1, which functions as a proinflammatory cytokine, from necrotic tumor cells creates a microenvironment similar to chronic inflammation; a condition known to contribute to the development of epithelial malignancies, particularly inflammation-associated cancer." (PMID 19476625, 2009). "In vitro use of oxaliplatin levels relevant to plasma concentrations obtained with therapy of patients with neoplastic disease, demonstrated in the present study, show that the extracellular release of HMGB1 from activated macrophage-like cells was substantially suppressed." (PMID 18179697, 2008). "Furthermore, evidence indicates that hyperthermia can trigger immunogenic cell death (ICD) in tumor cells, leading to the release of damage-associated molecular patterns (DAMPs), such as heat shock proteins 70/90 (HSP70/90), high mobility group box 1 (HMGB1), and adenosine triphosphate (ATP)." (PMID 41602425, 2026). "Additionally, IFNG boosted tumor angiogenesis via HMGB1 pathways, which could be mitigated by HMGB1 inhibition." (PMID 39945555, 2025). "Similarly, a report indicated that NETs could enhance the invasiveness of tumor cells by releasing matrix metalloproteinases (MMPs) and inducing the release of high-mobility group box 1 (HMGB1), promoting epithelial-mesenchymal transition (EMT)." (PMID 40102723, 2025). "Likewise, EP restrains tumor growth and metastasis in lymphoma, as well as hepatocellular and gastric carcinomas, by downregulating the HMGB1-RAGE axis and its downstream AKT/NF-κB and ERK/STAT3/SRC signaling pathways, thereby inhibiting proliferation and provoking cell death." (PMID 41465435, 2025). "In addition, tumor-associated macrophage-derived CXCL1 adds a further layer of regulation by activating IGF1R, leading to STAT3 phosphorylation and subsequent transcriptional upregulation of HMGB1, which drives autophagy and increases ABCG2 expression." (PMID 41465435, 2025). "Low rather than strong HMGB1 staining is often linked to an aggressive tumor phenotype." (PMID 40804938, 2025).
tumor (continued). "Additionally, HMGB1 induces CAF secretion of pro‐tumor factors (IL‐6, TGF‐β, VEGF) through a RAGE‐dependent mechanism, promoting tumor angiogenesis, immunosuppressive cell (Treg, MDSC) recruitment, and ECM remodeling—to build a stromal barrier favorable for tumor growth/metastasis." (PMID 41354099, 2025). "Conversely, under specific conditions, HMGB1 may also exert anti‐tumor functions." (PMID 41354099, 2025). "Thus, HMGB1 appears to be a crucial element of tumor mass and may be involved in tumorigenesis and metastasis." (PMID 40331953, 2025). "Although we did not directly assess these immune parameters, the interplay between HMGB1-mediated signaling and immune regulation represents a promising avenue for future research, particularly in the context of combination therapies targeting both tumor cells and the tumor microenvironment." (PMID 40559922, 2025). "In summary, HMGB1 coordinates key metabolic enzyme activity, substrate utilization, and energy stress responses through a “glycolysis prioritization‐mitochondrial plasticity” dual‐track model, laying the metabolic foundation for tumor proliferation and drug resistance." (PMID 41354099, 2025). "Similarly, Gastric cancer cell-derived exosome (GC-Ex) can activate neutrophil autophagy and promote tumor through the HMGB1/TLR4/NF-κB signaling pathway, which may be one of the underlying mechanisms for promoting TAN migration by TME." (PMID 40297580, 2025). "In these tumors lack of HMGB1 expression may represent a ”normal” status, while a lack of HMGB1 protein will indicate “HMGB1 deficiency” in most or all other tumor entities." (PMID 40804938, 2025). "In addition, temozolomide can induce the secretion of HMGB1 by tumor cells." (PMID 40297580, 2025). "However, some studies suggested that reduction of HMGB1 in the plasma could inhibit the 4T1 tumor growth by remodeling the TME." (PMID 40400098, 2025). "In parallel, accumulating evidence indicates that HMGB1 exerts profound effects on cancer cell survival that extend far beyond immune modulation, with intracellular and extracellular HMGB1 regulate stress-adaptive signaling networks that enable tumor cells to endure therapeutic insults." (PMID 41465435, 2025). "Additionally, our ongoing work indicates that platelets may interact with tumor cells through the HMGB1/LRRC32 signaling axis, thereby influencing the tumor immune microenvironment." (PMID 40514754, 2025). "Moreover, redox modifications of HMGB1 play an important role in MSC-tumor cell communication." (PMID 39940960, 2025). "Our findings indicate that Cdk2-/- tumor cells combined anthracyclines trigger a more robust series of immunostimulatory stress pathways than WT cells, including apoptosis stress, endoplasmic reticulum stress, HMGB1 release, and type-1 interferon response, stimulate DCs and T cells infiltration." (PMID 40557162, 2025). "This process also increased the release of intracellular DAMPs, including CRT, ATP, high mobility group box 1 (HMGB1), and mitochondrial nucleic acid (mtDNA), which could act as an “eat me” signal to promote phagocytosis of apoptotic tumor cells by dendritic cells." (PMID 40837737, 2025). "The overexpression of FAM72B may upregulate HMGB1 expression or enhance its functionality, indirectly influencing fibroblasts within the tumor microenvironment and facilitating the activation, migration, and proliferation of cancer-associated fibroblasts (CAFs)." (PMID 41153357, 2025). "Furthermore, inhibiting HMGB1 function could disrupt its role in tumor-promoting pathways, thereby enhancing the efficacy of existing treatments and improving patient survival rates." (PMID 41009692, 2025). "When tumor cells undergo ferroptosis, the accumulation of intracellular lipid peroxidation products and oxidative stress signals will lead to the rupture of the cell membrane and the release of a large number of immunogenic molecules, such as calreticulin, high mobility group box 1 (HMGB1), and ATP." (PMID 40559667, 2025).
tumor (continued). "Furthermore, HMGB1 knockdown reduced TEM/TE infiltration in the tumor microenvironment." (PMID 40082916, 2025). "Additionally, HMGB1 released during the ICD of tumor cells promotes IFNG secretion by CD8+ T cells." (PMID 39945555, 2025). "During ICD, dying tumor cells release damage-associated molecular patterns (DAMPs), including the surface exposure of calreticulin (CRT) and the extracellular secretion of heat shock proteins, high-mobility group box 1 (HMGB1) protein, and adenosine triphosphate (ATP) 9,10." (PMID 40083921, 2025). "HMGB1 expression was relatively uniformly elevated in most cancer types, which could be attributed to the broad and conserved role of HMGB1 as a “danger signal” in regulation of inflammatory activation, DNA repair and apoptosis in tumor cells." (PMID 40535567, 2025). "For instance, studies in vitro using human tumor cells treated with diphtheria toxin, which kills tumor cells, showed that dying cells with elevated autophagy selectively release HMGB1 without disrupting the cell membrane, whereas cells with blocked autophagy retain HMGB1." (PMID 39996754, 2025). "Therefore, HMGB1 is a potential target for tumor metabolic reprogramming." (PMID 39849606, 2025). "The inhibition of the PI3K/AKT/mTOR pathway not only restores apoptotic signaling in tumor cells but may also promote the release of apoptosis-related signaling molecules, such as DAMPs and HMGB1, and pro-inflammatory cytokines, such as IL-12 and IFN-γ, which activate anti-tumor immune responses." (PMID 39972480, 2025). "Furthermore, GPR65, identified as a lactate sensor in TAMs, detects lactate in the TME and initiates the downstream cAMP/PKA/CREB signaling pathway, promoting the release of high-mobility group box 1 (HMGB1) from TAMs and thereby accelerating tumor progression." (PMID 40165895, 2025). "Importantly, HMGB1 concentrations correlated positively with tumor aggressiveness—patients with high-grade tumors, muscle-invasive disease, multifocal lesions, and larger tumor diameters (≥3 cm) exhibited markedly higher urinary HMGB1 levels." (PMID 41009692, 2025). "Therefore, by maximizing the HMGB1 released only from cancer cells, it could be possible to suppress damage to the skin and inflict further damage only to the tumor." (PMID 40583575, 2025). "Due to the bidirectional regulation of HMGB1 on the tumor, it can promote the recruitment of macrophages during chronic release, and subsequently alter the tumor microenvironment to induce malignant transformation, and promote tumor cell proliferation, migration, and invasion." (PMID 37897664, 2024). "Nevertheless, this immunosuppressive effect of HMGB1 is primarily observed in established tumors where the tumor environment likely contains high levels of ROS, suggesting that the inactive oxidized form of HMGB1 may be responsible for the observed tolerogenic effects in such scenarios." (PMID 38994937, 2024). "Typically, macrophages infiltrated in tumors, named tumor-associated macrophages (TAM), shows M2-polarization characteristics and promote tumor malignant progression by secreting a variety of cytokines (e.g., TGFB1 and HMGB1) and chemokines (e.g., CCL17 and CXCL7)." (PMID 38576043, 2024). "Furthermore, 213Bi increased the release of DAMPs such as HMGB1 and Hsp70 in the conditioned medium from treated MC-38 cells, which may contribute to the anti-tumor response by activating DCs." (PMID 39355211, 2024). "Additionally, we investigate the downstream effectors of TOP1 in CC cells and identify TOP1-mediated tumor-promoting inflammatory features, characterized by alterations in the expression of CXCLs, HMGB1, IL-6, and STAT3/5, as well as several T cell regulatory genes." (PMID 39156107, 2024). "Furthermore, HMGB1 contributes to anti-tumor immunity through immunogenic cell death (ICD)." (PMID 38529373, 2024). "In contrast, HMGB1 may promote the sensitivity of tumor cells to radiotherapy." (PMID 38725632, 2024).
tumor (continued). "Thus, tumor-promoting TAN clusters with HMGB1 overexpression could serve as a prognostic indicator and gauge immunotherapeutic responses." (PMID 38877579, 2024). "Importantly, PDGFRA, known as the core regulator of angiogenesis, was the only TG that showed a negative correlation with OS at both the mRNA and protein levels, suggesting that HMGB1 might drive patients’ poor prognosis by promoting tumor angiogenesis." (PMID 39039072, 2024). "A previous study showed that HMGB1 could bind to RAGE, activate the MAPK signaling pathway, and then cause the activation of matrix proteases MMP9 and MMP2, degraded extracellular matrix, and promote tumor invasion and metastasis." (PMID 38577597, 2024). "Moreover, when B16F10, CT26, and MC38 cells were treated with increasing concentrations of zebularine for 3 days, we observed ATP release from tumor cells into the extracellular media in a dose-dependent manner as well as HMGB1 leaking from the nucleus into the cytoplasm by confocal microscopy." (PMID 38755254, 2024). "HMGB1 could also influence tumor microenvironment to regulate tumor progression." (PMID 38504159, 2024). "Another study showed that HMGB1, synergistically with ATP, could induce DCs to release interleukin‐1β (IL-1β), and HMGB1-specific antibodies can block the ability of IL-1β production in DCs after exposure to dying tumor cells." (PMID 38384466, 2024). "However, combination of docetaxel with hypo-fractionated RT particularly renders HPV-positive HNSCC tumor cells more immunogenic, characterized by increased release of HMGB1 and increased expression of immune stimulatory checkpoint molecules, with hypo-fractionated RT being the main trigger for it." (PMID 37857049, 2023). "However, although cell death and the release of HSP70 and HMGB1 was induced by RT in combination with docetaxel, we could not detect an increase of activation markers on hmDCs after co-culture with the tumor cells." (PMID 37857049, 2023). "Therefore, it was suggested that HMGB1-RAGE may be involved in tumor growth, but further investigation is needed since RAGE expression depends on histological tumor type and intracellular signaling." (PMID 37511951, 2023). "However, expression of RAGE in tumor tissue may be elevated so as to counterbalance the increased consumption due to elevated levels of HMGB1, but still lead to decreased concentrations of free, soluble RAGE in serum." (PMID 37894448, 2023). "As we all know, HMGB1 is a highly conserved non-histone nuclear protein and functions in the cytoplasm as an extracellular signaling protein in inflammation, cell differentiation, tumour progression, cisplatin resistance, and induces the hallmarks of ICD." (PMID 37537587, 2023). "Throughout this process, the tumor cells produce a group of signaling molecules known as damage-associated molecular patterns (DAMPs), including calreticulin (CRT) that exposes on the cell surface, secreted ATP, heat shock proteins (HSP70 and HSP90), and high mobility group protein 1 (HMGB1)." (PMID 37600822, 2023). "Therefore, while epithelial HMGB1 expression is not directly associated with survival, it is associated with an ‘immune cold’ tumour microenvironment, which is associated with poor survival." (PMID 36980751, 2023). "Besides AGEs and HMGB1, S100 group of proteins like S100A4 and S100A7 are also implicated in cancer growth, migration and angiogenesis via potent interaction with RAGE and potential re-modelling of tumour micro-milieu." (PMID 37970208, 2023). "Therefore, the observed correlations at the transcript level of the S100s and HMGB1 described in this manuscript could be the result of complex transcriptional regulation orchestrated by RAGE in the different cells of the tumor micro environment." (PMID 37627239, 2023). "However, there are reports suggesting that extracellular HMGB1 reduces tumor progression." (PMID 36831371, 2023).